CCL2 (C-C motif chemokine ligand 2)
Diseases named in the same sentence as CCL2 in open-access papers (continued):
Sharing a sentence is not in itself a finding about the gene and the disease.
cancer (continued). "Our data suggest that intra-epithelial macrophages respond to CCL2, which in turn can stimulate macrophages to produce Wnt-1, leading to disruption of E-cadherin junctions between early cancer cells." (PMID 29295986, 2018). "We conclude that HER2 signaling in cancer cells from early lesions activates NF-κB to induce CCL2, but that other myeloid cells also produce significant CCL2 mRNA." (PMID 29295986, 2018). "Downregulation of the IKBKE gene was previously reported to attenuate CCL2 release that led to cancer cell death." (PMID 30059519, 2018). "IL-1β was shown to increase cancer sphere formation and stem cell marker expressions in colon cancer, while IL-6, IL-8, CCL2 and transforming growth factor-β promoted breast cancer stemness." (PMID 30486830, 2018). "The fourth factor with potential role in cancer radioresistance, a chemokine CCL2/MCP1 critical for monocyte and MDSC recruitment, showed 1.06-fold increase after 7 weeks of CMT (p = 0.0017) and then decreased after patients completed therapy." (PMID 29541413, 2018). "This occurs through the production of chemoattracting agents such as chemokine C–X–C motif ligand (CXCL) 1 and chemokine (C–C motif) ligand 2 (CCL2) by dying cancer cells and subsequent recruitment of innate immune cells such as neutrophils and DCs to the TME." (PMID 29666625, 2018). "Among all the parameters, the highest SE in early stages of cancer was observed for CCL2 (in stage I of BC: 58.82%, in stage II: 58.54%)." (PMID 30151375, 2018). "CCL2 is dominantly expressed by many human carcinomas and detection of CCL2 in TAMs themselves even indicates the existence of an amplification loop for their recruitment." (PMID 30245686, 2018). "A consistent pattern has emerged as carcinoma derived bone metastases use CCL2 and IL-8 in tandem within the bone microenvironment to promote osteolysis and growth." (PMID 29930538, 2018). "Next, we examined the dynamic change of secreted levels of CCL2 in different time points at 1:1 ratio of macrophages to cancer cells." (PMID 28533507, 2017). "CCl2 together with its cognate CCR2 play key roles in cancer metastasis by sustaining cancer cell proliferation and survival, stimulating cancer cell migration and invasion, and inducing deleterious inflammation and angiogenesis." (PMID 28487672, 2017). "Cells were collected after 24 hours co-culture and the RTQ-PCR results showed that, transcription level of CCL2 of Cal-27 cells increased to the peak at 1:1 ratio of macrophages to cancer cells and started to decrease at 1:2 ratio." (PMID 28533507, 2017). "To further examine the impact of Oligo-Fucoidan on IL-6 and CCL2 secretion from cancer cells, we treated HCT116 cells with etoposide and Oligo-Fucoidan (400 μg/ml) or etoposide alone for 24 h before incubating the cells in serum-free media for another 48 h." (PMID 28928376, 2017). "Chemokines (such as CCL2), which are produced by cancer cells, promote the recruitment of peripheral monocytes to the cancer microenvironment, thereby promoting the recruitment of monocytes from the bone marrow to peripheral blood." (PMID 28583114, 2017). "CCL2 has been suggested to promote cancer cell survival, regulate CAF-carcinoma cell interactions and fuel late-stage carcinoma progression." (PMID 28545495, 2017). "Further clarification is required to understand the targeting of the CCL2/CCR2 pathway in cancer therapy." (PMID 28424406, 2017). "The CCL2 is a proinflammatory chemokine reported to regulate the recruitment of myeloid cells into inflamed sites and tumors that promotes cancer development and progression." (PMID 28878142, 2017). "It is well known that NF-κB plays a critical role in inflammation and is a transcription factor for a number of immune-related genes (IL-6, CCL2, among others) involved in immune responses; thus, it plays a dual role in promoting and inhibiting cancer." (PMID 29312296, 2017).
cancer (continued). "Some genes are important factors in the immune system of cancer patients, such as CCL2, CCL20, CCL5, CCR7, IFNG and P450 family." (PMID 28384236, 2017). "The disruption of CCL2/CCR2 chemokine signaling has been shown to suppress cancer cell proliferation, migration and invasion." (PMID 28424406, 2017). "In our work, doxycycline not only suppressed the cancer cell-derived chemo-attractants for monocytes, e.g., IL-6 and CCL2, but also directly impaired the migration activity of mouse PBMCs." (PMID 28178994, 2017). "As a result of this interaction a more favorable adaptation of cancer cells to the new tissue environment is achieved by increasing their growth rate but also by inducing the secretion of the chemokine (C-C motif) ligand 2 (CCL2)." (PMID 29312881, 2017). "There are reports shown that fibroblasts involve in the cross-talk of cancer cells and fibroblasts by secreting CCL2, CCL5, CXCL1, CXCL6, CXCL12, IL6, CXCL16 and others." (PMID 28465475, 2017). "Cancer cell secreted CCL2 participates in the generation of a protumorigenic niche by inducing an influx of brain metastasis-promoting Iba1+/CCR2+ myeloid cells." (PMID 29312881, 2017). "CCL2 neutralizing antibodies, which have shown promising therapeutic efficacy in several cancer models." (PMID 28424406, 2017). "The disruption of CCL2/CCR2 chemokine signaling has been shown to suppress cancer cell viability and metastasis." (PMID 28424406, 2017). "CCL2, a member of C-C chemokine family, is known as a major cytokine for the recruitment of myeloid cells including MDSCs from the bone marrow to cancer tissues, and induction of CCL2 in various cells by HMGB1 has also been reported." (PMID 28536706, 2017). "For example, it was recently reported that some CAFs and pre-cancerous hepatocytes recruit MDSCs via IL-6 and CCL2-mediated pathway, respectively, thereby protecting cancer cells from immune cells." (PMID 29234059, 2017). "Fibroblasts are also the main source of CCL2 in response to tissue injury, cytokine stimulation, and cancer cell interaction." (PMID 27541266, 2016). "These networks are interconnected with a subnetwork of genes that are associated with cancer progression, such as COX2, TGFβ, CCL2, CXCL2, MMP9, and MMP13." (PMID 26831400, 2016). "This study demonstrates a novel approach to target CCL2 and reveals important insight into the effects of CCL2 gene silencing on necrosis, autophagy, cancer stem cell renewal and macrophage recruitment." (PMID 27283985, 2016). "Because of its correlation with the progression of cancer, the CCL2/CCR2 signaling pathway has generated increasing interest in the past few years." (PMID 27409666, 2016). "Regarding CCL2 expression in ccRCC, microarray data derived from Oncomine showed significantly higher expression of CCL2 in cancer tissue compared with normal kidney parenchyma." (PMID 27666332, 2016). "Although first described as a chemotactic molecule with physiological roles in regulating inflammation, recent studies have revealed a pro-tumorigenic function for CCL2 in favoring cancer development and subsequent metastasis." (PMID 26885690, 2016). "Migration of macrophages to the anatomical sites of tumors has been described to be mediated by MCP-1/CCL2 in a variety of cancers." (PMID 27034006, 2016). "Monocyte chemoattractant protein-1 (MCP-1)/CCL2 plays an important role in the initiation and progression of cancer." (PMID 26834744, 2016). "Inhibition of galectin-1 in CAF decreases the expression of monocyte chemotactic protein-1 (MCP-1/CCL2), which has been implicated in contributing to an immunosuppressive TME, and as an inducer of cancer progression." (PMID 27050278, 2016).
cancer (continued). "For example, among the 16 DE genes found exclusively by PD in the TNF signaling pathway, the average expression level of CCL2 was ranked at the top 3.2% and 1% of all the measured genes in the cancer and normal samples, respectively." (PMID 27796338, 2016). "CCL2 can further stimulate cell proliferation and enhance survival once cancer cells have been recruited to metastatic sites." (PMID 26885690, 2016). "Elevated levels of CCL2 and/or CCL5 are associated with poor outcomes due to the high incidence of metastasis in various types of cancer." (PMID 27448966, 2016). "Cell lines derived from MMTV-neu carcinomas in wild type and Ccr2-/- backgrounds secrete CCL2 in culture." (PMID 27820834, 2016). "Neutrophils treated with a2NTD (a2Neuɸ) showed increased secretion of IL-1RA, IL-10, CCL-2 and IL-6 that are important mediators in cancer related inflammation." (PMID 26460736, 2015). "While CCL2 itself induces some cancer cell proliferation, CCL2 conditioning of the macrophages increases the effect that these cells have on cancer cell proliferation." (PMID 26174804, 2015). "We have shown that CCL2 is required for driving LPS-induced activation of macrophages, and that CSF-1, secreted from cancer cells, induces polarisation of macrophages." (PMID 26174804, 2015). "Further, we show that macrophage associated proteins, colony-stimulating factor (CSF)-1 and C-C motif ligand (CCL)-2, stimulate macrophages and are responsible for the effects of cancer cells on macrophages." (PMID 26174804, 2015). "CCL2 is involved in other cancer types, including bladder and prostate, by promoting the migration and invasion of cancer cells." (PMID 25695619, 2015). "Other chemokines such as CXCL12 (Sdf-1) and CCL2 (MCP-1) are secreted by various cancer types and function as autocrine growth factors as well as chemo-attractants for progenitor cells and monocytes/macrophages." (PMID 25743773, 2015). "We have shown that there is a cycle mediated by the cytokines CSF-1 and CCL2, whereby cancer cells induce macrophage proliferation and phenotypic changes, and macrophages stimulate cancer cell proliferation." (PMID 26174804, 2015). "CSF-1 and CCL2 are known modulators of the fate of macrophages, both driving the production of M2 cells and being correlated to poor prognosis in cancer." (PMID 26174804, 2015). "We have shown that cancer cells and macrophages have mutual effects on each other, and that the cytokines CSF-1 and CCL2 are important mediators of this interaction." (PMID 26174804, 2015). "The proliferative response of cancer cells to CCL2-treated macrophage CM is probably due to activation of other receptors in the cancer cells by soluble factors secreted from macrophages." (PMID 26174804, 2015). "CCL2 is a pro-inflammatory chemokine involved in cancer metastasis by promoting monocyte attraction and angiogenesis." (PMID 26694746, 2015). "In this study we aim to further understand the mutual effects between cancer cells and macrophages by investigating the role of CSF-1 and CCL2 stimulation on this interaction and promotion of an M2 phenotype within the context of canine mammary carcinoma." (PMID 26174804, 2015). "To determine the effect of inhibition of CSF-1 and CCL2 signalling on cancer cells we utilised the small molecule inhibitors of CSF-1R (GW2580) and CCR2 (RS102895)." (PMID 26174804, 2015). "The PC-3 High Invasive/U-937 co-culture supernatants showed increased CCL2 and Gro-α levels when compared to PC-3 High Invasive cancer cell supernatants alone." (PMID 26317041, 2015). "Four of the cytokines screened in this array were present at high levels in the co-culture supernants; however, only the MCP-1/CCL2 cytokine was increased in the co-cultures above the cancer cells alone when tested by ELISA." (PMID 26317041, 2015). "Infiltration of tumors by circulating MSCs is enhanced by CXCR4, CXCR12 and CCL2 secreted by cancer cells." (PMID 25695337, 2015).
cancer (continued). "The crucial roles of ANGPT2 and CCL2 have been already established in the mechanism of cancer metastasis." (PMID 25883937, 2015). "One of the predominant roles of CCL2 is the recruitment of monocytes/macrophages in a plethora of inflammatory diseases, including cancer." (PMID 26358505, 2015). "During their differentiation into osteoblasts, mesenchymal stem cells secrete CCL2, which is believed to mediate the migration of cancer cells, a process that is partially inhibited by anti-CCL2." (PMID 25165728, 2014). "Similar findings were obtained for CCL2, another member of the “cancer-related chemokine cluster” that was addressed in our previous study of non-transformed cells." (PMID 24598028, 2014). "Cancer cells often secrete M2-type cytokines such as IL-10, CCL2/3/4/5/7/8, CXCL12, VEGF, and platelet-derived growth factor (PDGF) to recruit monocytes/M0 macrophages and direct them toward an M2 phenotype." (PMID 24507759, 2014). "The data support that CCL2/12 blockade functions to block emergent cancer hallmarks of specific importance to pleural fluid production, such as inflammation and vascular homeostasis." (PMID 23967166, 2013). "It has been shown that matrix metalloproteinase-1 (MMP-1) causes activation of PAR1 leading to expression of the pro-angiogenic secreted chemokines CXCL8 (IL-8), CXCL1 (GRO-α), and CCL2 (MCP-1) by the cancer cells." (PMID 24384839, 2013). "Among these many chemokines monocyte chemoattractant protein -1/chemokine (C-C motif) ligand 2 (MCP-1/CCL2), a member of the CC chemokines subfamily, is of particular relevance to cancer invasion and metastasis." (PMID 23349788, 2013). "CAF-secreted CCL2 also increased the activation of Notch signalling in carcinoma cells via induction of p38 mitogen-activated protein kinase (MAPK) signalling, thereby stimulating mammosphere formation." (PMID 24216702, 2013). "These cells were exposed to microenvironmental pressures, and the expression of a cancer-related chemokine cluster was used as readout for the malignancy potential (CCL2, CCL5, CXCL8, CXCL10)." (PMID 24213226, 2012). "As with DMXAA-regulated stromal RNAs, several cancer cell-derived RNAs, including CCL2 (MCP-1), IL-8, IL-6, CXCL1 (Melanoma Growth Stimulating Activity/GRO1), also concurred with the protein data." (PMID 22415295, 2012). "The CCL2 chemokine is involved in promoting cancer angiogenesis, proliferation and metastasis by malignancies that express CCR2 receptor." (PMID 21943176, 2011). "There are also gene products related to cancer, respiratory disease, and inflammation, such as chemokine (C-C motif) ligand 2 (CCL2; also known as MCP 1)." (PMID 21757418, 2011). "Emerging evidence suggests that the CC chemokine CCL2/MCP-1 (monocyte chemotactic protein-1) plays pleiotropic roles in cancer development." (PMID 21826248, 2011). "In addition, we cocultured cancer cells with ADSCs after silencing CCL2 or HIF‐1α in the cancer cells, thereby inhibiting CCL2 secretion." (PMID 41160815, 2026). "However, the migratory effect was reduced by CM collected from the coculture of cancer cells and ADSCs in which CCL2‐induced lipolysis was inhibited." (PMID 41160815, 2026). "Besides, CAFs secrete immunosuppressive chemokines such as CCL2 and, together with cancer stem cells (CSCs), promote chemoresistance." (PMID 41355964, 2026). "To determine whether the increased CCL2 in coculture‐derived CM was secreted by cancer cells, we tagged the cancer cells with GFP and cocultured them with ADSCs in the 3D coculture system." (PMID 41160815, 2026). "This cascade of events reactivates the FA–HIF‐1α–CCL2 axis within the cancer environment." (PMID 41160815, 2026). "To assess whether cancer cell‐derived CCL2 regulates lipid metabolism in adipose tissue, we used a neutralizing antibody (nAb‐CCL2) to inhibit CCL2 during 3D coculture of cancer cells and ADSCs." (PMID 41160815, 2026).
cancer (continued). "Thus, our data support the existence of a functional FAs/HIF‐1α/CCL2 axis in cancer cells under increased FA supply." (PMID 41160815, 2026). "Since CCL2 is a major player in chemoattraction of immune cells, particularly monocytes, this finding suggests that the presence of cancer cells and CAFs in TME might impair CCL2 production by endothelium and decrease immune recruitment." (PMID 40348600, 2025). "Similarly, the CCL21/CXCL10 and CCL2 axis has been identified as a key mediator of neural remodeling, PNI, and cancer‐associated pain in PDAC." (PMID 40981722, 2025). "In addition to CCL2, CCL22, and IL-10, TAM-associated markers CCL5 and SPP1 (secreted phosphosprotein 1, also known as osteopontin, OPN) are promising targets for novel cancer immunotherapy." (PMID 40806751, 2025). "Moreover, when ECs were in co‐culture with cancer cells and CAFs, we observed a global down‐regulation in ECs of more than half of the immunomodulatory genes within our panel, including CCL2." (PMID 40348600, 2025). "CCL2 plays a pivotal role in cancer progression and metastasis." (PMID 40806751, 2025). "Normal B and cancer 1 clusters shared inflammatory markers CCL2, TNFRSF12A, and IL1R1, pathways including TNFα, IL, and Myc signaling, and activity of inflammation, hypoxia, and lipid metabolism–associated transcription factors NFATC2, ARNT, PPARA, and PPARGC1A." (PMID 40215177, 2025). "Similarly, CCL2 can promote transmigration and extravasation of cancer cells via the CCL2-CCR2 astrocyte–cancer cell axis." (PMID 40076927, 2025). "Thus, organosulfur components lower adipogenesis, adipose tissue inflammation, cancer development, and CCL2 and CXCL12 release." (PMID 40076892, 2025). "CCL2 plays an important role in the survival, proliferation, migration and colonization of distant organs of cancer cells through paracrine and autocrine mechanisms, which runs through all stages of cancer development." (PMID 41341593, 2025). "CCL2 could facilitate the infiltration of immune cells into the tumor microenvironment, contributing to the inflammatory response and cancer pain sensation." (PMID 40579593, 2025). "Activation of CCL2 promotes the proliferation, migration and invasion of cancer cells." (PMID 41341593, 2025). "Therefore, CCL2-regulated ncRNAs serve as novel cancer biomarker and therapeutic target for cancer patients." (PMID 41341593, 2025). "Furthermore, in malignant tumors, CAFs promote tolerance by recruiting and inhibiting regulatory T cells through the secretion of CCL2, CCL5, etc.." (PMID 38612943, 2024). "Most importantly, the concentration of CCL2 and IL-6, which were secreted only by the MSCs, were doubled in the co-cultures suggesting that cancer cells can induce the secretion of some factors, like pro-inflammatory cytokines which could support their growth." (PMID 38674102, 2024). "For more detailed analysis we selected activated CCL2 (also known as MCP-1) which encodes a ligand that binds and activates its cognate receptor CCR2, plays multifaceted roles in myeloid immune cells, and acts as an oncogene in some cancer types." (PMID 39689089, 2024). "In addition to CCL2, three other MCP chemokines exist—CCL7 (MCP-3), CCL8 (MCP-2), and CCL13 (MCP-4)—and are implicated in cancer progression." (PMID 39409924, 2024). "Interestingly, most genes were up-regulated in multiple groups; genes for chemokines (Ccl2, Ccl5), cell adhesion (Icam1, Lgals3) and a growth factor (Ngf) were up-regulated in at least three non-cancer groups." (PMID 39254423, 2024). "The upregulation of CCL2/CCR2 is vital for the monocyte recruitment to transform into macrophages that can be transformed into M2 polarized macrophages for impairing CD8+ T cell-induced anti-cancer immune responses." (PMID 38997297, 2024).